SPG11 (SPG11 vesicle trafficking associated, spatacsin)
Diseases named in the same sentence as SPG11 in open-access papers (continued):
Sharing a sentence is not in itself a finding about the gene and the disease.
spastic paraplegia 11 (4 papers, 2022 to 2025). "SPG11 (spastic paraplegia 11) encodes for the spatacsin protein and although its function not being completely understood, is thought to control gene regulation, vesicular trafficking and axonal maintenance." (PMID 40395983, 2025). "SPG11 is associated with the recessive hereditary spastic paraplegia 11, which can have a complex phenotype in some cases." (PMID 38153678, 2024). "Our second proband that is homozygous for NM_001160227.2: c.5454dupA: p.Glu1819Argfs Ter11 variant as a novel mutation of the SPG11 gene is a likely pathogenic variant that has a significant risk factor for spastic paraplegia 11 disease." (PMID 36239107, 2022).
Alzheimer disease (3 papers, 2018 to 2025). A progressive, neurodegenerative disease characterized by loss of function and death of nerve cells in several areas of the brain leading to loss of cognitive function such as memory and language. "The fact that tideglusib has been approved by FDA and has been tested in clinical trials of Alzheimer’s Disease, Autism Spectrum Disorder and Myotonic Dystrophy renders a potential availability also for SPG11 patients." (PMID 30574063, 2018).
neuropathy (3 papers, 2016 to 2022). A disorder affecting the nervous system that manifests with pain, tingling, numbness, and/or muscle weakness. "In summary, we established the differentiation of iPSC derived MNs from SPG11 patients with neuropathy and provided evidence of axonal mitochondrial alterations including altered mitochondrial morphology, polarization, and transport in SPG11 MNs." (PMID 34326717, 2021). "The neuropathy was compared with other typical SPG11 cases with complex HSP and was significantly worse." (PMID 27544499, 2016). "It is noteworthy for clinicians to consider SPG11 testing in early onset complex HSP or where there is a combination of severe neuropathy and spasticity." (PMID 27544499, 2016). "We aimed to investigate mitochondria in MNs derived from SPG11 patients with neuropathy." (PMID 34326717, 2021). "The severe neuropathy in our case is consistent with neuropathy being a major feature in some, but not all patients with SPG11 mutations and a complex HSP phenotype as is confirmed in the Cypriot family." (PMID 27544499, 2016). "Thus, it would be interesting to investigate whether mitochondrial alterations are also present in MNs derived from SPG11 patients without neuropathy." (PMID 34326717, 2021).
Spasticity (3 papers, 2020 to 2024). A motor disorder characterized by a velocity-dependent increase in tonic stretch reflexes with increased muscle tone, exaggerated (hyperexcitable) tendon reflexes. "In the current study, none of the iNPH patients who were found to have heterozygous SPG11 mutations presented with spasticity or peripheral neuropathy." (PMID 38100419, 2023).
Tremor (3 papers, 2022 to 2024). An unintentional, oscillating to-and-fro muscle movement about a joint axis. "In HSP-MD cases, SPG11 was the commonest genotype among those who initially manifested with tremor (76.9%) and learning/cognitive problems (76%)." (PMID 36441344, 2023).
Autosomal recessive spastic paraplegia type 11 (2 papers, 2016 to 2024). "Variants in SPG11 are the common cause of autosomal recessive spastic paraplegia type 11." (PMID 27900367, 2016).
Cerebellar atrophy (2 papers, 2022). Cerebellar atrophy is defined as a cerebellum with initially normal structures, in a posterior fossa with normal size, which displays enlarged fissures (interfolial spaces) in comparison to the foliae secondary to loss of tissue. "In the HSP group, “ear of the lynx” and thinning corpus callosum are common and characteristic findings for SPG11 (case 11 and 12) and SPG15 (case 13), especially for SPG11, and non-specific white matter lesions (case 14/SPG35) and cerebellar atrophy (case 15/SPG46) have been described." (PMID 35578252, 2022).
frontotemporal dementia (2 papers, 2018 to 2021). Frontotemporal dementia (FTD) comprises a group of neurodegenerative disorders, characterized by progressive changes in behavior, executive dysfunction and language impairment, as a result of degeneration of the medial prefrontal and frontoinsular cortices. "Moreover, some of the genes identified in ALS patients are also causative for other neurodegenerative disorders, such as C9orf72 and TARDBP for frontotemporal dementia (FTD) and Parkinson’s disease, and SPG7 and SPG11 for hereditary spastic paraplegia, indicating shared pathomechanisms." (PMID 35052424, 2021).
motor neuron degeneration (2 papers, 2022 to 2023). "More importantly, SPG11-HSP patients also suffer from amyotrophy, a sign of lower motor neuron degeneration." (PMID 35778567, 2022).
motor neuron diseases (2 papers, 2018 to 2022). "SPG11-HSP is also a motor neuron disorder that is primarily characterized by upper motor neuron loss and thinning of the corpus callosum." (PMID 35778567, 2022). "Interestingly, mutations in SPG11 encoding spatacsin, were also found in other motor neuron diseases such as AR juvenile-onset amyotrophic lateral sclerosis (ALS5) and AR Charcot-Marie-Tooth disease." (PMID 30574063, 2018).
muscular dystrophies (2 papers, 2020 to 2024). "Another example for this was a family in which we identified a known pathogenic homozygous SPG11 variant via WES (AQ54), whereas the a prior diagnosis of this family was muscular dystrophy." (PMID 32214227, 2020).
Obesity (2 papers, 2022 to 2025). Accumulation of substantial excess body fat. "As SPG11 results in rapidly progressing motor disability, immobility might be the primary cause of obesity in SPG11." (PMID 36432490, 2022). "In SPG11, comorbidities such as obesity, reduced mobility, and adipokine dysregulation appear integral to disease expression, with progressive motor impairment driving immobility, increased adiposity, inflammatory imbalance, and worsening metabolic stress." (PMID 41228418, 2025). "Elevated leptin levels provide evidence for a central nervous system-mediated mechanism of obesity in SPG11." (PMID 36432490, 2022). "For example, obesity was reported in only 1 out of 38 SPG11 patients in one study but in 14 out of 18 SPG11 patients in another cohort." (PMID 36432490, 2022). "Of note, in different cohorts of different sizes, obesity was observed in SPG11 at varying frequencies." (PMID 36432490, 2022). "A recent Brazilian study of 20 SPG11 patients reported obesity in 25% of patients and provided first evidence of altered hypothalamic volume in SPG11." (PMID 36432490, 2022). "A high prevalence of obesity in SPG11 has been reported by several groups, but a more detailed characterization has been lacking." (PMID 36432490, 2022). "Insight into the etiopathogenesis of obesity and lymphedema in SPG11 may not only extend current knowledge on the mechanism of SPG11-linked neurodegeneration but also provide novel targets to interfere with the metabolic phenotype." (PMID 36432490, 2022). "Our data indicate a link between obesity and hypothalamic neurodegeneration in SPG11 and imply that specific metabolic interventions may prevent obesity despite severely impaired mobility in SPG11." (PMID 36432490, 2022). "Because lipid metabolism impairment is central to SPG11 pathology (autophagy–lysosomal dysfunction with lipid accumulation) and obesity is common, dietary strategies emphasizing healthy lipid profiles, caloric balance, and antioxidant support could be particularly useful." (PMID 41228418, 2025). "The etiology of obesity in SPG11 may be different from the well-described metabolic syndrome because none of the SPG11 patients was affected by diabetes, arterial hypertension, or coronary artery disease." (PMID 36432490, 2022).
Paraparesis (2 papers, 2018 to 2023). Weakness or partial paralysis in the lower limbs. "SPG11 patients with paraparesis had decreased paracentral and thalamic metabolism." (PMID 30627115, 2018).
spastic ataxia (2 papers, 2013 to 2022). "Thus, ARSACS should be part of the differential diagnosis in spastic ataxias with TCC, like e.g. SPG11, SPG15 or GBA2." (PMID 23497566, 2013).
Spastic paraparesis (2 papers, 2024 to 2026). Partial loss of the ability to move the lower limbs accompanied by spasticity of the lower limbs. "We report a case of a 47-year-old man with an eight-year history of progressive gait disturbance and spastic paraparesis who was found to carry a likely pathogenic homozygous missense variant in the SPG11 gene (c.5381T>C; p.Leu1794Pro)." (PMID 42078221, 2026).
spinal muscular atrophy (2 papers, 2020 to 2025). A motor neuron disease that affect the muscles, and characterized by muscle weakness and atrophy resulting from progressive degeneration and irreversible loss of the anterior horn cells in the spinal cord (i.e., lower motor neurons) and the brain stem nuclei. "Finally, the SPG11 p.Ser559Thr which was identified in a pyramidal sALS patient and the three DYNC1H1 variants, a gene previously associated with AD CMT2 and spinal muscular atrophy (SMA) phenotypes, were all classified as VUS." (PMID 32397312, 2020).
ventricular dilatation (2 papers, 2022 to 2023). "INPH-associated mutations identified in this study affected two other genes, MYO7A and SPG11, that have previously been shown to cause hydrocephalus or ventriculomegaly." (PMID 38100419, 2023). "The typical “ear of the lynx” sign, thin corpus callosum, and ventricular dilatation were seen in all the cases of SPG11 and SPG15." (PMID 35572931, 2022). "Because all of the iNPH patients displayed ventriculomegaly and experienced symptomatic improvement after CSF drainage, our findings are in alignment with the observation that HSP patients display enlarged ventricles and raise the possibility that heterozygous SPG11 mutations may contribute to iNPH." (PMID 38100419, 2023).
-motor polyneuropathy (1 paper, 2016). "In this study, we identified novel compound heterozygous mutations in SPG11 in a complex HSP family with thin corpus callosum and severe axonal sensory-motor polyneuropathy as a late manifestation of the disease." (PMID 27544499, 2016).
Argininemia (1 paper, 2021). Arginase deficiency is a rare autosomal recessive amino acid metabolism disorder characterized clinically by variable degrees of hyperammonemia, developing from about 3 years of age, and leading to progressive loss of developmental milestones and spasticity in the absence of treatment. "The most frequent MRI abnormality was thin corpus callosum (TCC), which was present in 10/42 subjects (5 with SPG11, 2 with SPG15, 1 each with argininemia, SPG30 and SPG64)." (PMID 34782662, 2021).
axonal motor neuropathy (1 paper, 2016). "Distal axonal motor neuropathy and neurogenic changes were detected in 23 subjects: most of the SPG7, SPG11, SPG15 and SPG35 patients, the eldest three SPG3a patients, a minority of SPG4 (5 out of 23) and one SPG5 subject." (PMID 27077743, 2016).
Brain atrophy (1 paper, 2020). Partial or complete wasting (loss) of brain tissue that was once present. "All these SPG11 studies, with concomitant spatacsin mutations involved in axonal stability and transport, presented additional findings such as TCC, WM hyperintensities, brain atrophy, and impaired DTI indexes in areas related to CST tracts." (PMID 32765386, 2020). "The common structural findings at MRI of the studies on SPG11 patients consisted in the presence of thin corpus callosum (TCC), WM hyperintensities and brain atrophy." (PMID 32765386, 2020).
cortical atrophy (1 paper, 2018). "Although the onset and patterns of cognitive symptoms and cortical atrophy present in SPG11 patients are markedly different from those observed in AD patients, our data suggest that GSK3β over-activation may be a common molecular denominator of both diseases." (PMID 30574063, 2018).
distal myopathy (1 paper, 2021). Distal myopathy refers to a group of muscle diseases which share the clinical pattern of predominant weakness and atrophy beginning in the feet and/or hands. "Other allelic neurological disorders with the same gene associations are ataxia with oculomotor apraxia (SETX), HSP (ALS2, SPG11, ERLIN1, and DDHD1), JPLS (ALS2), dHMN (SIGMAR1), distal myopathy (GNE), and distal SMA (BICD2)." (PMID 34946884, 2021).
fecal incontinence (1 paper, 2018). Involuntary passage of stool from the rectum. "In a Dutch study of 18 HSP patients with a mutation in the SPG11 gene, (SPG11) eight were reported to have developed urinary and fecal incontinence." (PMID 29661209, 2018).
Frontal cortical atrophy (1 paper, 2014). Atrophy of the frontal cortex. "Impaired cognition identified in SPG11 patients may be attributed to frontal lobe dysfunction and progressive frontal cortical atrophy." (PMID 24794856, 2014).
juvenile ALS (1 paper, 2020). "In spite of the relative abundance of SPG11 variants, this gene is associated with AR HSP with thin corpus callosum and juvenile ALS under recessive disease models." (PMID 32397312, 2020).
leukodystrophies (1 paper, 2024). "While the impact of neuroinflammation is an emerging and potentially treatable aspect in neurodegenerative diseases and leukodystrophies, the role of immune cells in SPG11–HSP patients is unknown." (PMID 38305941, 2024).
lymphedema (1 paper, 2022). Excess fluid collection in tissues, causing swelling. "Lymphedema and dysregulated adipose homeostasis are frequent symptoms in SPG11-HSP and may be directly linked to hypothalamic adipocytokine resistance leading to a dysfunctional brain–adipose axis." (PMID 36432490, 2022). "Swelling of the lower extremities caused by lymphedema has been described in SPG11 patients and may further contribute to an increased body weight." (PMID 36432490, 2022).
myotonia congenita (1 paper, 2023). "However, it could be due to an incidental coexistence of myotonia congenita rather than an additional symptom of SPG11-HSP, given that a pathogenic CLCN1 mutation was identified." (PMID 37396771, 2023).
scoliosis (1 paper, 2024). A congenital or acquired spinal deformity characterized by lateral curvature of the spine. "Counting of scoliosis-related genes indicated that NF1, FBN1, LAMA2 and SPG11 led the top list of genes concerned with scoliosis." (PMID 39502335, 2024).
Sensory neuropathy (1 paper, 2021). Peripheral neuropathy affecting the sensory nerves. "However, the features found in HSP patients with progressive UMN signs, sensory neuropathy, and an absence of bulbar involvement distinguish this disease from the SPG11-JALS clinical presentation." (PMID 34946884, 2021).
Sepsis (1 paper, 2025). Sepsis is defined as life-threatening organ dysfunction caused by a dysregulated host response to infection. "Survivors of sepsis often show neurocognitive impairment, similarly severe infections may put patients with SPG11 at risk for an accelerated neurodegeneration." (PMID 41138668, 2025).
Urinary incontinence (1 paper, 2016). Loss of the ability to control the urinary bladder leading to involuntary urination. "Gastrointestinal problems for persons with HSP have previously been documented in a Dutch study, in which combined fecal and urinary incontinence was identified among seven of 18 patients aged 13 to 46 years with complex HSP, specifically SPG11 mutation." (PMID 27412159, 2016).
neurodegenerative disease (5 papers, 2022 to 2025). A disorder of the central nervous system characterized by gradual and progressive loss of neural tissue and neurologic function. "This mini scoping review has several strengths that enhance its contribution to understanding personalized nutrition in neurodegenerative diseases, particularly SPG11." (PMID 41228418, 2025). "This study highlights the promising role of personalized nutrition as a crucial strategy for managing neurodegenerative diseases, including rare conditions such as SPG11." (PMID 41228418, 2025). "Considering the biological variability characteristic of SPG11 and other neurodegenerative diseases, future personalized dietary plans must incorporate each patient’s unique genetic, metabolic, and microbiota profile." (PMID 41228418, 2025). "Few studies have directly investigated nutritional interventions tailored for SPG11, so much of the discussion extrapolates findings from related neurodegenerative diseases." (PMID 41228418, 2025). "LRRK2–PD microglia as well as microglia from other neurodegenerative diseases additionally displayed increased phagocytic activity, paralleling our finding in IFNγ treated SPG11 iMGL." (PMID 38305941, 2024). "Since the peripheral immune response and its crosstalk with neuroinflammation is of increasing relevance in other neurodegenerative diseases, we additionally investigated peripheral immunity in a larger SPG11 cohort." (PMID 38305941, 2024). "Our data add to previous evidence of dual neurodevelopmental and -degenerative disease mechanisms in SPG11." (PMID 35906604, 2022). "The observed increase in peripheral inflammation in the present SPG11–HSP patient cohort is comparable to other neurodegenerative diseases, where the contribution of inflammation is well-established, supporting our findings of neuroinflammatory disease signatures in the limited postmortem tissue." (PMID 38305941, 2024). "Although rTMS is expected to be a therapeutic tool for neurodegenerative diseases, no previous studies have applied rTMS to treat motor symptoms in SPG11-HSP." (PMID 37273711, 2023).
peripheral neuropathy (5 papers, 2015 to 2023). A disorder affecting the peripheral nervous system. "Peripheral neuropathy has been infrequently reported in SPG11-HSP." (PMID 37396771, 2023).
neurological disorders (3 papers, 2018 to 2021). "Here, we report finding SPG11 mutations in 19 available individuals of eight families who are affected with neurological disorders." (PMID 32383541, 2020). "Mutations in SPG11 (OMIM 610844) which encodes spatacsin (after “spasticity with thin or atrophied corpus callosum syndrome protein”) are associated with various neurological diseases." (PMID 32383541, 2020). "We have reported SPG11 mutations in eight families with neurological diseases." (PMID 32383541, 2020).
infection (2 papers, 2025). The state of being infected such as from the introduction of a foreign agent such as serum, vaccine, antigenic substance or organism. "A limitation of this study is that the exact molecular events leading to the hyper-responsiveness of the non-canonical inflammasome remain elusive, and clinical data are currently insufficient to assess whether patients suffering from SPG11 or SPG48 are prone to infection-related complications." (PMID 41138668, 2025). "Moreover, our findings suggest that patients with either SPG11 or SPG48 may be prone to infection-triggered complications." (PMID 41138668, 2025).
movement disorder (2 papers, 2024). Neurological conditions resulting in abnormal voluntary or involuntary movement, which may impact the speed, fluency, quality and ease of movement. "We, therefore, analyzed a previously unpublished postmortem brain from a late-stage SPG11 patient from the Erlangen movement disorder clinic (UKER), whose clinical history was reported earlier." (PMID 38305941, 2024).
SPG11 also shares sentences with these, for which no sentence is quoted: cerebellar ataxia (4 papers); deafness (3); Cerebral atrophy (2); developmental delay (2); multiple sclerosis (2); periodontal disease (2); schizophrenia (2); abscess (1); Action tremor (1); albinism (1); Anxiety (1); arterial hypertension (1); Atrophy (1); autism (1); autism spectrum disorder (1); autosomal dominant disease (1); autosomal recessive cerebellar ataxia (1); autosomal recessive dHMN (1); cervical dystonia (1); chronic periodontitis (1); congenital ichthyosis (1); congenital myopathy (1); coronary artery disease (1); Crohn disease (1); delirium (1); diabetes (1); Dyskinesia (1); early infantile epileptic encephalopathy (1); Encephalopathy (1); epilepsy (1).
A further 27 diseases each share a sentence with SPG11 in 1 paper.